CD34 (CD34 molecule)
Diseases named in the same sentence as CD34 in open-access papers (continued):
Sharing a sentence is not in itself a finding about the gene and the disease.
infection (continued). "This view is also suggested by the difference in CD34+DNAM-1brightCXCR4+ cell progeny phenotype detected in lung tumor (85-90% T-cells) compared to the considerably lower one (20-30%) reported in patients with infection (CMV, HIV, HCV)." (PMID 38390333, 2024). "We also showed that when the virus-exposed infection-resistant CD34+ cells in vivo were derived ex vivo and re-engrafted into a fresh secondary stromal microenvironment in vivo, in the absence of the virus’ influence, recovery and resurgence of hematopoiesis would occur." (PMID 38721526, 2024). "Despite high levels of viral replication, we did not observe clinical signs of infection (such as weight loss or fever) in any of the CD34+ hu-mice models." (PMID 39204240, 2024). "However, Kalejta and colleagues went on to show increased IFNβ and CXCL10 transcripts in UL138-M16STOP infection in CD34+ HPCs, concluding that UL138 functions in immune evasion, degrading STING to abate a type-1 interferon response." (PMID 37289831, 2023). "Our method using CD34 + cells does not require culture expansion, minimizing the risk of infection or contamination, and eliminating the waiting period associated with culture expansion before cell transplantation." (PMID 37798633, 2023). "Infection may occur directly, with the virus infecting endothelial cells, or indirectly, with the virus potentially infecting B cells and CD34+ hematopoietic progenitor cells to transit these barriers." (PMID 37896889, 2023). "Analysis of viral DNA in both HCMV WT- and HCMVΔUL8-infected CD34+ HPCs at 14 days post-infection (dpi) indicated similar amounts of HCMV genomes in both cell populations, demonstrating that the lack of reactivation was not due to genome loss during the culture period." (PMID 37772824, 2023). "Importantly, the H3K27 demethylase, lysine demethylase 6B (KDM6B; formerly known as JMJD3), is inhibited by the viral protein product of UL138, a latently expressed protein required for this phase of infection in CD34+ HPCs." (PMID 37439556, 2023). "According to our theory in the present study, CD133 and CD34 may serve as intercellular adhesion molecules during infection by DENV, indicating that these cells could aggregate as a homing-associated cell adhesion molecule for attachment of the virus." (PMID 37386042, 2023). "The early rapid IR of CD3+ T cells was affected by whether there was infection before transplantation (P=0.034), the number of transfused CD34+ cells (P=0.022) and the implantation time of ANC (P=0.021)." (PMID 35693743, 2022). "In addition, tropism analysis in six of the eight donors harboring proviral HIV-1 DNA in CD34+ cells as detected by qPCR assay found infection with R5 HIV-1." (PMID 36230931, 2022). "Indeed, disruption of the entire UL33 ORF or UL33’s G-protein coupling motif (the ‘DRY’ motif) results in a failure to reactivate from latency following infection of CD34+ HPCs, despite the ability of each mutant virus to maintain viral genomes." (PMID 34663377, 2021). "Importantly, spread to and infection of the bone marrow leads to the establishment of a latent reservoir within CD34+ HPCs." (PMID 34663377, 2021). "EGFR is an important receptor for efficient infection and establishment of latency in CD34+ HPCs." (PMID 34663377, 2021). "This reveals that CD133+ cells are more spontaneous in virus reactivation and more susceptible to active infection, whereas CD34+ cells are not very significant in reactivation and predominantly latent." (PMID 33981874, 2021). "However, the biological relevance and importance of these receptors in infection monocytes or CD34+ HPCs and in cell signaling remain unresolved." (PMID 34025614, 2021). "Of specific importance is infection of bone marrow derived and myeloid lineage cells, such as peripheral blood monocytes and CD34+ hematopoietic progenitor cells (HPCs) because of their essential role in dissemination of the virus and for the establishment of latency." (PMID 34025614, 2021).
infection (continued). "US28 is expressed in naturally infected human peripheral blood cells during periods of latency, reactivation in lung transplant recipients, and in the model of HCMV latency using CD34+ HPCs, monocytes, and in monocyte-derived macrophages during active infection." (PMID 34025614, 2021). "The antagonism between UL135 and UL138 is important to the outcome of infection in CD34+ HPCs." (PMID 32630219, 2020). "This was attributed to the fact that the mobilized CD34+ HPC levels of the patients were possibly associated with the bone marrow reserves, and that patients with low bone marrow reserves were somewhat susceptible to infection." (PMID 32512672, 2020). "UL133 is expressed in CD34+ HPCs at 2 and 5 days post infection (dpi)." (PMID 32630219, 2020). "Because presence ofM.tb DNA in the CD34+ PBMC cell fraction could represent a microbiological marker of infection, it has potential for better sensitivity and specificity of LTBI diagnosis." (PMID 32832853, 2020). "CMV miR-US22 targets EGR1 in the context of infection in CD34+ HPCs." (PMID 31725811, 2019). "CD4+ frequencies in CD34+ cells before infection were lower than those in CD34− cells." (PMID 30761146, 2019). "Expression of many of these genes was lower at 6 days postinfection, which is consistent with previous data that demonstrated that infection of CD34+ HPCs induces a brief stage of viral gene expression after which most of the viral genome is silenced, probably through genome modification." (PMID 31431555, 2019). "This “emergency” deployment may be mechanistically interpreted to support the model of a CD34+ travel trajectory toward inflamed peripheral tissues—in addition to SLT—when an increased turnover of lymphoid cells occurs at sites of infection/inflammation." (PMID 31555276, 2019). "We have previously shown that JUNV infection up-regulates TfR1 in CD34+ hematopoietic stem cells." (PMID 31695702, 2019). "Therefore, we use both fibroblasts and CD34+ HPCs in our studies to understand how the virus manipulates host pathways and the significance of this biology to infection." (PMID 31725811, 2019). "Analysis of the 366 cells that expressed viral transcripts revealed low expression levels, and as in CD14+ monocytes, the low viral gene expression that we measured in these cells correlated with the expression pattern of the late stage of lytic infection (comparing CD34+ cells to cluster 1)." (PMID 29535194, 2018). "More recently, EGFR signalling has been shown to improve the efficiency of infection of CD34+ cells as well, with EGFR-blocking antibodies and inhibitors of EGFR/PI3K signalling leading to less internalisation of virus particles if applied prior to viral infection." (PMID 29547547, 2018). "We speculate that this is because UL138 expression, although lower, is still sufficient to prevent lytic infection in the CD34+ cells." (PMID 30021158, 2018). "Hematopoietic failure was reported early in infection and in the absence of CD34+ infection and not linked to plasma viral load." (PMID 28279181, 2017). "However, infection of CD34+ cells leads to a reduced number of cells undergoing enucleation (to ~70–80%)." (PMID 28871080, 2017). "We used lentiviral infection to inhibit expression of ATG7 in immunopurified CD34+ CML cells." (PMID 29228587, 2017). "However, compared to 4 days post infection, IER5 levels in Kasumi-3 cells and CD34+ HPCs infected with NR-1 significantly decreased at later stages of infection (7–10 dpi), while levels of CDC25B expression were restored." (PMID 27824944, 2016). "Infection of CD34+ hematopoietic bone marrow progenitor cells." (PMID 26996968, 2016). "We also analyzed the effect of PI3K inhibition on the WT infection in CD34+ HPCs." (PMID 27218650, 2016).
infection (continued). "The efficiency of various steps in the course of infection of adult marrow-derived CD34+ cells relative to the efficiency in permissive 293T cells was evaluated using qPCR with established PCR primer sequences, and using the chromosomal RNase-P gene as our Ref." (PMID 26945863, 2016). "We thus asked whether the co-repressor associates with the HCMV genome by performing KAP1-specific chromatin immunoprecipitation-deep sequencing (ChIP-seq) analyses on material isolated from human CD34+ HSC at 7 days post-TB40-E infection." (PMID 25846574, 2015). "In contrast, in a non-permissive cell, the virus cannot overcome these intrinsic blocks and continued suppression of the MIEP allows the establishment of a quiescent infection that can ultimately result in viral latency in, for instance, a monocyte or CD34+ cell." (PMID 25147545, 2014). "Apoptosis was a direct result of infection in MSCs, whereas, it might be induced by paracrine factors in CD34+ HSCs." (PMID 24339969, 2013). "The major breakthroughs in our understanding of HIV-1 cis and trans infection stem from discovery of simple methods for deriving large numbers of myeloid DC from CD34+ bone marrow stem cells using various growth factors and more importantly from blood monocytes using IL-4 and GM-CSF." (PMID 24278768, 2013). "Using different techniques including flow cytometry, quantitative RT-PCR, plaque assay, immunofluorescence and confocal microscopy, we demonstrated that CD34+ HSCs and MSCs supported a productive infection of H5N1 virus, although to a lesser degree in CD34+ HSCs." (PMID 24339969, 2013). "With this thought, we investigated the fate of MSCs and CD34+ HSCs after infection." (PMID 24339969, 2013). "We also tested infection of CD34+ blood stem cells in umbilical cord blood." (PMID 23409116, 2013). "Apoptosis observed in a majority of infected MSCs was likely due to direct infection, whereas, apoptosis in CD34+ HSCs might be induced by paracrine factors as apoptotic signals were observed in uninfected CD34+ HSCs population." (PMID 24339969, 2013). "This was consistent with the observation that LSK CD34− CD135− cells increased during infection." (PMID 22194881, 2011). "The observation that JUNV infection up-regulates TfR1 in CD34+ cells could represent a viral dissemination strategy at least in hematopoietic bone marrow cells." (PMID 20419155, 2010). "Likewise, as CD34+ HPCs continue to divide following infection, it is currently unknown whether genomes are diluted out by cell division or if only a small subset of the cells initially infected can maintain genomes." (PMID 40736257, 2025). "While standardized procedures were used for cord blood collection, elusive differences in cord blood—such as subclinical infection during pregnancy, irritation of the coagulation cascade, or genetic polymorphisms—might affect the level of CD18 expression in CD34+ cells." (PMID 40003604, 2025). "Notably, the highest CD34+ cell levels coincided with maternal or infant infections." (PMID 41147034, 2025). "To exclude the possibility that the observed inhibition of committed progenitors’ clonogenicity could be due to the expression of cytotoxic mediators produced by the infection of non-CD34+ cells present in the culture, we studied the effect of direct viral interaction with CD34+ purified cells." (PMID 41143413, 2025). "To explore whether the uptake of exogenous serine is mediated by the amino transporter, we depleted SLC38A1 by using shRNAs in CD34+ cells via lentiviral infection, leading to the increase of serine levels in the conditioned medium (CM) from cells with SLC38A1 knockdown." (PMID 37055385, 2023). "However, these immune cells become pathogenic to this virus, eliciting a profuse cytokine storm through the cytokine dysregulation in these cells; interestingly, this is in an indirect manner following infection of the CD133+CD34+/− ESPC through this virus’ primary receptor ACE2 on the cell surface." (PMID 38155835, 2023).
infection (continued). "Finally, it was recently published that HCMV utilizes secreted protein pUL7, miR-US5-1, and miR-UL112-3p to reduce the proapoptotic transcription factor FOXO3a, which in turn reduces expression of proapoptotic gene BCL2L11 and prevents virus-induced apoptosis after infection of CD34+ HPCs." (PMID 34025614, 2021). "To determine the impact of these modifications on IGF2BP1 function, we transduced CD34+ cells from four healthy adult donors with the parental SIiP virus or versions that included the 2A-puromcyin (SI2AP) or 2A-ZsGreen (SI2AZG) cassette at equivalent multiplicities of infection (MOIs)." (PMID 32154328, 2020). "The functional and phenotypic differences observed for ULb’ genes between fibroblasts and CD34+ HPC or any other cell types may be due to the differences in the cell biology inherent to each context of infection and the resulting profile of viral gene expression." (PMID 32630219, 2020). "Moreover, the expanded CD34+ cells could increase the count nadir of NEU and PLT and reduce the susceptibility to infection following transplantation, thus enhancing survival." (PMID 31196160, 2019). "For instance, the exclusion of pp71 from the nuclei in CD34+ cells during the initial stages of infection combined with the recruitment of the polycomb repressor complex by the viral lncRNA4.9 transcript to the MIEP may contribute to establishment and maintenance of the latent state." (PMID 25147545, 2014). "Indeed, a recent report suggests that Langerin-positive dendritic cells degrade internalized HIV-1, reducing transfer to CD4+ T cells in the mucosa, while others show that activated CD34-positive Langerhans cells increase trans infection of permissive target cells." (PMID 18637194, 2008). "The results showed that the CD45+Lin-CD34+ISM1+ population tended to decrease during infection, while the CD45+Lin-CD150+ISM1+ populations significantly increased during infection." (PMID 40572169, 2025). "When this virus was used to infect primary expanded CD34+ cell cultures at an MOI of 3, GFP+ cells (~50 in 1.6 × 104) were detectable by day 1 post-infection (P.I.)using live-cell imaging." (PMID 40872823, 2025). "(F) Monocyte progenitors (MPs) (CD3−, NK1.1−, B220−, CD117+, CD34+, CD16/32hi, Ly6C+, CD135−, CD115+; orange box) in the bone marrow of infected WT and Il27−/− mice throughout infection." (PMID 41396163, 2025). "Furthermore, our in vitro models of human CD34+ HPC-induced MK differentiation represent a tool to study the interactions of SARS-CoV-2 variants with specific hematopoietic target cells and to test new drugs preventing SARS-CoV-2 binding and subsequent infection of these cells." (PMID 38257782, 2024). "In the case of Hu-NSG (CD34+), seven cytokines were detected, with a predominance of the IFN-α response (3/3 mouse) and IFN-γ (2/3 mouse) by day 21 post-infection." (PMID 39204240, 2024). "This difference in infection outcome was statistically significant when comparing survival curves among hu-SGM3 (PBMCs), hu-NSG (CD34+), hu-EXL (CD34+), and hu-SGM3 (CD34+) (p < 0.001)." (PMID 39204240, 2024). "While IE1 and IE2 transcripts are mostly driven by the MIEP during lytic infection, recent work has uncovered that expression of genes from the MIE locus are driven by two alternative promoters, iP1 and iP2, in bone marrow-derived CD34+ HPCs." (PMID 39661658, 2024). "CD34+ HPCs provide a critical reservoir of latent HCMV infection and infection of HPCs contributes to the hematopoietic abnormalities observed in transplant patients." (PMID 37346032, 2023). "We concluded that DENV NS1 secreted from cells during the initial phase of infection interacted with a pool of CD133 and CD34 cells and remained co-localized." (PMID 37386042, 2023). "We infected CD34+ HPCs with a WT or ΔUL138STOP virus in the presence or absence of the JAK1/2 inhibitor, Ruxolitinib, added at the time of infection." (PMID 37289831, 2023).
infection (continued). "Flow cytometric analysis showed that after 4 weeks of infection, CD133 and CD34 gating percentages were higher at a certain time point but decreased on days 5, 20, and 30 in DENV-infected cells in comparison to uninfected UCBs." (PMID 37386042, 2023). "A total of 1 × 104 CD34 + cells were infected by a CTS Cytotune-iPS 2.1 reprogramming kit, and colonies emerged between 8 and 11 days after infection." (PMID 38093328, 2023). "The evidence for direct infection of HPCs with HCMV is well established, including in CD34+ HPCs isolated from adult (bone marrow) and immature cells (cord blood or fetal liver)." (PMID 37346032, 2023). "In agreement with the CCR5-tropic transduction of CD34+CD38+ progenitors in vitro in our study, both X4 and R5 HIV-1 appear to target HSPCs, whereby R5 infection/transduction is restricted to less immature progenitors." (PMID 36230931, 2022). "Latent infection often occurs in less-differentiated cells such as CD14+ monocytes, CD34+ HPCs, and immature dendritic cells." (PMID 35214602, 2022). "Accordingly, studies using humanized mice observed infection of CD34+CD38+ progenitors by HIV-1 strains of all tropisms, including CCR5-tropic strains, albeit at much lower infection rates than by CXCR4-tropic or dual-tropic strains." (PMID 36230931, 2022). "Our siRNA results suggested a more pronounced requirement for FoxO3a than FoxO1 during HCMV lytic infection, echoing the role we found for FoxO3a in HCMV reactivation from latency in the THP-1 model and in CD34+ human progenitor cells (HPCs)." (PMID 35946797, 2022). "Our strategy will be limited to R5-tropic but not X4 tropic virus as we see a high expression of CXCR4 receptor in CD34+CD90+ HSCs and this explain the reason for X4 tropic infection in the HSCs." (PMID 35359982, 2022). "In patients, CD34+ hematopoietic progenitor cells (HPCs) are a critical reservoir of latent HCMV (7, –, 9) and infection of HPCs contributes to the hematopoietic abnormalities observed following transplantation (10, –, 13)." (PMID 35012351, 2022). "Although the infection rates of different HSPC subsets were low (mostly < 1.5%), CD34+ cells in bone marrow samples of PLHIV were a frequent (8/11 donors), but not consistent source of proviral HIV sequences in our study." (PMID 36230931, 2022). "Thus, cell sorting based on viability, CD34 expression, and a fluorescent marker is critical in order to begin an experiment with a pure population of infected cells and to take into account differences in infection rates between viruses based on, for example, variations in viral titers." (PMID 35012351, 2022). "Infection of naïve cells and of their cell precursors (CD4+ thymocytes, CD34+ multipotent hematopoietic progenitor cells) within these organs has been put forward to explain why X4 viruses deplete CD4TL more than R5 viruses." (PMID 33872329, 2021). "More γδT cells were expressing CD80, CD11b, or PD-1 post-infection (p < 0.05), while less γδT cells were expressing CD34, CD62L, and CD127 post-infection (p < 0.05)." (PMID 33588839, 2021). "Hu-PBMC mice were significantly more likely to survive VARV infection compared to hu-BLT and hu-CD34+, controlling for dose (high dose p = 0.004, low dose p = 0.008)." (PMID 34547055, 2021). "More CD3+ γδT+ cells were expressing CD80, CD11b, and PD-1 post-infection (p < 0.05), while less CD3+ γδT+ cells were expressing CD34, CD127, and CD62L in the infected mice (p < 0.05)." (PMID 33588839, 2021). "We predict that infection of CD133+ and CD34+ cells in the UCB serve as reservoirs for the amplification of DENV in UCB prior to the virus reaching the fetus and facilitate vertical transmission." (PMID 33981874, 2021). "From this work, a model emerges whereby high levels of EGR1 in CD34+ HPCs primes these cells for expression of UL138 and the establishment of latency upon infection." (PMID 31725811, 2019).